RUSC2 (RUN and SH3 domain containing 2)
Description:
Associates with the adapter-like complex 4 (AP-4) and may therefore play a role in vesicular trafficking of proteins at the trans-Golgi network.
Synonyms: Iporin; KIAA0375; MRT61
Tractability: Small molecule: a structure with a bound ligand is known. Antibody: UniProt places it where antibodies can reach, with high confidence; its Gene Ontology location is reachable by antibodies, with high confidence. PROTAC: ubiquitination databases record sites on it.
Gene: Protein-coding gene on chromosome 9 (35,489,712 to 35,561,898, forward strand). Ensembl gene ENSG00000198853.
Subcellular location: Cytoplasm, cytosol; Cell membrane
Gene Ontology:
Molecular function: protein binding; small GTPase binding
Cellular component: cytoplasmic vesicle; extracellular exosome; plasma membrane; cytoplasm; cytosol
Genetic constraint (gnomAD): Loss-of-function variants: 34 observed, 118.1 expected, observed/expected ratio (o/e) 0.29, 90% interval 0.22 to 0.38. The upper end of that interval is the gene's LOEUF score, 0.38, which puts it in group 1 of 6, group 1 being the genes least tolerant of losing a copy. Missense variants: 1,671 observed, 1,912.9 expected, observed/expected ratio (o/e) 0.87, 90% interval 0.84 to 0.91. Synonymous variants: 749 observed, 773.28 expected, observed/expected ratio (o/e) 0.97, 90% interval 0.91 to 1.03.
Gene-disease validity (ClinGen):
ClinGen rates the evidence that RUSC2 causes each of these diseases.
intellectual disability, autosomal recessive 61 (autosomal recessive): Moderate. An autosomal recessive non-syndromic intellectual disability that has material basis in an autosomal recessive mutation of the RUSC2 gene on chromosome 9p13.
Homologues: Orthologues: chimpanzee RUSC2 (99% identical), macaque RUSC2 (98% identical), rabbit RUSC2 (91% identical), dog RUSC2 (91% identical), pig RUSC2 (91% identical), rat Rusc2 (87% identical), mouse Rusc2 (87% identical), tropical clawed frog rusc2 (49% identical), zebrafish rusc2 (22% identical). Paralogues in human: RUSC1 (16% identical).
Diseases named in the same sentence as RUSC2 in open-access papers:
RUSC2 is named in the same sentence as 7 diseases in open-access papers, as found by Europe PMC text mining. Sharing a sentence is not in itself a finding about the gene and the disease. The quoted sentences say what the papers report.
lung carcinoma (2 papers, 2021 to 2024). "Duan has demonstrated that RUSC2 is commonly expressed in diverse lung cancer cells, knockdown of RUSC2 effectively inhibits the migration of lung cancer cells, and RUSC2 regulates the progression of lung cancer through epidermal growth factor receptor (EGFR) signaling." (PMID 38725627, 2024). "RUSC2 interacts with the SHD domain of GIT2 and reduces GIT2 degradation, which regulates lung cancer progression through EGFR signaling." (PMID 34642262, 2021).
neuroblastoma (1 paper, 2024). Neuroblastoma (NB) is the most common solid, extracranial childhood tumor. "Mutations in RUSC2 in neuroblastoma have been identified as potential drivers." (PMID 38725627, 2024).
tumor (2 papers, 2021 to 2024). "Conversely, WNK2, RUSC2, CYP3A4, and RGN, among the significantly downregulated genes in the non-tumor iP organoids, have been described as tumor suppressors downregulated in HCC." (PMID 34328417, 2021).
neurodevelopmental disorder (1 paper, 2024). A behavioral and cognitive disorder with onset during the developmental period that involves impaired or aberrant development of intellectual, motor, or social functions. "Previous investigations have reported patients with variants of RUSC2, a Rab35 effector, which present with a neurodevelopmental disorder." (PMID 38432637, 2024).
RUSC2 also shares sentences with these, for which no sentence is quoted: Astrocytoma (1 paper); endothelial dysfunction (1); neurological disorder (1).